RNU6-532P (RNA, U6 small nuclear 532, pseudogene)
Gene: Small nuclear RNA gene on chromosome 7 (96,330,638 to 96,330,744, forward strand). Ensembl gene ENSG00000207045.
Homologues: Orthologues: chimpanzee U6 (100% identical), macaque U6 (95% identical), guinea pig U6 (86% identical), rat U6 (86% identical), mouse Gm23579 (82% identical). Paralogues in human: RNU6-1145P (88% identical), RNU6-1316P (88% identical), RNU6-35P (88% identical), RNU6-38P (88% identical), RNU6-1 (87% identical), RNU6-116P (87% identical), RNU6-15P (87% identical), RNU6-2 (87% identical), RNU6-20P (87% identical), RNU6-25P (87% identical), RNU6-310P (87% identical), RNU6-393P (87% identical), and 1288 more.